ALKBH5 (alkB homolog 5, RNA demethylase)
Diseases named in the same sentence as ALKBH5 in open-access papers (continued):
Sharing a sentence is not in itself a finding about the gene and the disease.
Wilms tumor (2 papers, 2020 to 2021). An embryonal neoplasm characterized by the presence of epithelial, mesenchymal, and blastema components. "Stratification analysis did reveal some significant relationships between these SNPs and Wilms tumor risk in certain subgroups, indicating a weak influence of ALKBH5 gene SNPs on susceptibility to Wilms tumor." (PMID 33790968, 2021). "We have previously genotyped two SNPs (rs1378602 and rs8400) in the ALKBH5 gene to identify if they were associated with Wilms tumor susceptibility in a large multicenter case-control study." (PMID 33790968, 2021). "A total of 414 Wilms tumor cases and 1199 healthy controls were genotyped for ALKBH5 rs1378602 and rs8400 polymorphisms by TaqMan." (PMID 32091154, 2020). "The current clinical analysis provided only a weak impact of ALKBH5 gene SNPs on susceptibility to Wilms tumor." (PMID 32091154, 2020). "To date, this is the first report focusing on the association between the ALKBH5 gene SNPs and Wilms tumor risk." (PMID 32091154, 2020). "Herein, we evaluated the association of single nucleotide polymorphisms (SNPs) in the m6A modification gene ALKBH5 and Wilms tumor susceptibility in a large multi‐center case‐control study." (PMID 32091154, 2020). "Our data suggested a weak association between ALKBH5 gene SNPs and Wilms tumor risk in Chinese children." (PMID 32091154, 2020). "Thus, it is of a great necessity to investigate the association between ALKBH5 gene SNPs and the risk of Wilms tumor." (PMID 32091154, 2020). "Collectively, our results demonstrate that ALKBH5 SNPs may exert a weak influence on susceptibility to Wilms tumor." (PMID 32091154, 2020). "Herein, we attempted to investigate whether ALKBH5 gene SNPs could link to the risk of Wilms tumor." (PMID 32091154, 2020). "In this study, we conducted the first case‐control study of 414 Wilms tumor cases and 1199 controls to yield new insights into the role of m6A modification gene ALKBH5 SNPs in Wilms tumorigenesis." (PMID 32091154, 2020).
abortion (1 paper, 2025). the ending of pregnancy by removing a fetus or embryo before it can survive outside the uterus. "But in a recurrent spontaneous abortion model, overexpressed ALKBH5 reduced stromal VEGF secretion and impaired M2 macrophage differentiation and recruitment, thus the molecular mechanisms underlying macrophage polarization mediated by ALKBH5 awaited further investigation." (PMID 40264760, 2025).
adenoma (1 paper, 2022). A neoplasm arising from the epithelium. "M6A modification is regulated by RNA methyltransferase and demethylase, hence we assessed the expression of methyltransferase (METTL3, METTL14 and WTAP) and demethylase (FTO and ALKBH5) in both adenoma and CRC." (PMID 35012593, 2022).
adenovirus infection (1 paper, 2023). "We then established the ALKBH5 knockdown cell lines via adenovirus infection in PANC-1 and MIA PaCa-2 cells." (PMID 37149664, 2023).
allergic asthma (1 paper, 2022). A asthma with a basis in a pathological type I hypersensitivity reaction. "The m6A writers METTL14 and the m6A eraser ALKBH5 are decreased significantly both in mRNA and protein level in lung of mice with allergic asthma compared with control." (PMID 36250525, 2022). "Thus, the m6A methylation of IL17RB mRNA, regulated by demethylase ALKBH5, may play an important role in the pathogenesis of allergic asthma, and might be a new therapeutic target." (PMID 36250525, 2022).
Aortic dissection (1 paper, 2022). Aortic dissection refers to a tear in the intimal layer of the aorta causing a separation between the intima and the medial layers of the aorta. "For example, m6A demethylase ALKBH5 facilitate the progression of aortic dissection via inhibition of the maturation of pri-miR-143-3p in an m6A-dependent manner." (PMID 35836571, 2022).
astrocytoma (1 paper, 2022). "In a single-cell RNA-seq analysis of astrocytoma dataset, 23 out of 28 m6A-RMRs (82%) (except ALKBH5, IGF2BP1, IGF2BP2, IGF2BP3, and G3BP2) were in the medium to high expression levels in malignant cells of astrocytoma." (PMID 35211628, 2022).
atrial fibrillation (1 paper, 2023). A disorder characterized by an electrocardiographic finding of a supraventricular arrhythmia characterized by the replacement of consistent P waves by rapid oscillations or fibrillatory waves that vary in size, shape and timing and are accompanied by an irregular ventricular response. "Atrial fibrillation patients with a high level of the eraser ALKBH5 showed low expression levels of the reader HNRNPA2B1 and writer METTL3." (PMID 37435047, 2023).
Atrophy (1 paper, 2024). Any weakening or degeneration, especially through lack of use. "Local injection of R-2-HydroxyglutaraTe (R-2HG) in denervation-induced skeletal muscle atrophy inhibits FTO and ALKBH5 expression, promotes m6A modification, and ameliorates muscle atrophy." (PMID 39125931, 2024).
cardiomyopathy (1 paper, 2025). A disease of the heart muscle or myocardium proper. "Recent studies have noted increased mortality in ALKBH5-deficient mice, whereas overexpression of ALKBH5 modulates Rasal3 mRNA stability in an m6A-dependent manner, activating the RAS/RAF/ERK pathway to inhibit CMs apoptosis and alleviate doxorubicin-induced cardiomyopathy (DIC)." (PMID 40001550, 2025).
colitis (1 paper, 2025). Inflammation of the colon. "In a rat model of experimental colitis, administration of palmatine, a biologically active alkaloid, was found to prevent body weight loss and improve pathology by increasing m6A levels, which entailed the downregulation of Alkbh5." (PMID 40254698, 2025).
colon adenocarcinoma (1 paper, 2021). "To comprehensively understand the role of ALKBH5 and YTHDF1 in tumor immunity, we analyzed the transcriptome profiling data of colon adenocarcinoma from The Cancer Genome Atlas (TCGA) and Gene Expression Omnibus (GEO)." (PMID 34079761, 2021). "ALKBH5 and YTHDF1 may remarkably influence the immune contexture of colon adenocarcinoma." (PMID 34079761, 2021). "This study aimed to determine the relationship between ALKBH5/YTHDF1 and immunological characteristics of colon adenocarcinoma (COAD)." (PMID 34079761, 2021).
COVID-19 (1 paper, 2022). A disease caused by infection with severe acute respiratory syndrome coronavirus 2. "COVID-19 patients with elevated expression levels of CBLL1, METLL16, and RBM15B presented elevated expression levels of ALKBH5 while elevated METTL14 and ZC3H13 expression demonstrated a negative association with ALKBH5." (PMID 35655464, 2022).
E. coli infection (1 paper, 2024). "FACS analyses revealed that total intracellular G-CSFR protein expression was substantially reduced in ALKBH5-deficient dHL-60 cells during E. coli infection, consistent with our observation of decreased G-CSFR protein expression on the surface of neutrophils." (PMID 38114747, 2024).
endometrial adenocarcinoma (1 paper, 2021). "Furthermore, aberrant expression of erasers was also detected, and both FTO and ALKBH5 were significantly decreased in women with endometrial adenocarcinoma versus controls." (PMID 34149936, 2021).
epilepsy (1 paper, 2025). A brain disorder characterized by episodes of abnormally increased neuronal discharge resulting in transient episodes of sensory or motor neurological dysfunction, or psychic dysfunction. "We also detected elevated levels of both FTO and ALKBH5 in human TLE, both of which have been reported to remove m6A, suggesting a more complex and nuanced regulation of m6A in human epilepsy than in mouse." (PMID 40693462, 2025). "Overall, in both mouse and human epilepsy, there are changes in the abundance of enzymes regulating m6A (notably METTL3 in both mouse and human and FTO and ALKBH5 in human TLE), although no gross changes in m6A were detectable using colorimetric assays." (PMID 40693462, 2025).
Fever (1 paper, 2020). Body temperature elevated above the normal range. "This decreased mRNA expression of METTL14 was associated with WBC and M; this decreased mRNA expression of ALKBH5 was associated with CRP, N%, L%, NLR, C3, and fever; and the decreased mRNA expression of YTHDF2 was associated with L%, NLR, C3, and fever." (PMID 32583611, 2020).
gastric tumors (1 paper, 2023). "The K235 acetylation level of ALKBH5 was substantially higher in the primary liver and gastric tumors than that in their corresponding adjacent nontumor liver and gastric tissues." (PMID 37369679, 2023). "Finally, we determined the levels of K235 acetylation and ALKBH5, KAT8, and HDAC7 in ten pairs of matched fresh primary liver and gastric tumor samples and adjacent nontumor liver and gastric tissues." (PMID 37369679, 2023).
gynecologic cancer (1 paper, 2024). "Abnormal expression of FTO and ALKBH5 is closely associated with the occurrence of various diseases, such as leukemia, infertility, and obesity, bladder cancer, etc. m6A demethylase also plays an important role in gynecological cancers." (PMID 38343637, 2024). "All these reports indicate that the function of FTO and ALKBH5 in gynecologic cancer mainly depends on the demethylation of m6A, and they play an important role in the occurrence and development of gynecologic cancer." (PMID 38343637, 2024).
Hepatitis (1 paper, 2025). Inflammation of the liver. "In contrast, other m6A regulators, including METTL3, METTL14, WTAP, FTO, ALKBH5, YTHDC1, and YTHDC2, exhibited different protein expression patterns during ConA-induced hepatitis." (PMID 40092485, 2025).
intracerebral hemorrhage (1 paper, 2026). A cerebrovascular disorder characterized by bleeding into one or both cerebral hemispheres including the basal ganglia and the cerebral cortex. "METTL3 mRNA expression was higher in mice with collagenase-induced intracerebral hemorrhage than in controls, whereas WTAP, FTO and ALKBH5 expression was lower in mice with collagenase-induced intracerebral hemorrhage than in controls." (PMID 41601663, 2026).
ischemic cardiomyopathy (1 paper, 2024). Ischemic cardiomyopathy is a cardiomyopathy in which a weakness in the muscle of the heart due to inadequate oxygen delivery to the myocardium with coronary artery disease being the most common cause. "We observed that the transcriptional profile of ALKBH5 increased in left ventricle tissue of patients with ischemic cardiomyopathy (ICM) (P = 0.000242) or dilated cardiopathy (DCM) (P = 0.019) compared with donors with nonfailing (Control) myocardium." (PMID 39294131, 2024).
latent infection (1 paper, 2023). "We showed that on silencing ALKBH5 there was a significant increase in viral copy numbers even during latent infection." (PMID 36918845, 2023).
lentivirus infection (1 paper, 2023). Virus diseases caused by the Lentivirus genus. "Supported by CLIP of demethyltransferases showing FTO but not ALKBH5 bound with m6A site on Spi2a, we overexpressed FTO in BMDMs using lentivirus infection for further investigations." (PMID 36864027, 2023).
limb ischemia (1 paper, 2021). A ischemia that involves the limb. "We found that the effects of transient adenoviral ALKBH5 gene silencing in mice after hind‐limb ischemia are promising." (PMID 34047466, 2021). "In contrast, global ALKBH5 KO mice show increased angiogenesis after hind‐limb ischemia with markedly increased m6A level." (PMID 34047466, 2021). "Similarly, ALKBH5 KO mice showed significantly enhanced blood flow restoration on days 7–21 following hind‐limb ischemia." (PMID 34047466, 2021).
lipid metabolism disorders (1 paper, 2024). "Overexpression of ALKBH5 increases FABP5 expression in a m6A-IGF2BP2 dependent manner, leading to lipid metabolism disorders.The research report that inhibition of ALKBH5 could promote m6A modification of CCL28 mRNA and increase its stability." (PMID 38918701, 2024).
liver disease (1 paper, 2023). "Further, expression of the m6A METTL3 writing complex, erasers (demethylases: FTO and ALKBH5), and m6A readers (RBPs) are altered in human NAFLD and in experimental models of liver disease and contribute to NAFLD, HCC, and CCA." (PMID 37628704, 2023).
lymphoid leukemia (1 paper, 2025). A malignant lymphocytic neoplasm of B-cell or T-cell lineage involving primarily the bone marrow and the peripheral blood. "While the m6A demethylases FTO and ALKBH5 are recognized for their crucial roles in various cancers, their impact on lymphoid leukemia remains uncertain." (PMID 40435251, 2025).
malignant brain tumor (1 paper, 2020). "Additionally, ALKBH5 was found to be linked with the devastating malignant brain tumor glioblastoma through the ALKBH5-FOXM1-mediated pathway; in this milieu, ALKBH5 enhances glioblastoma tumorigenesis." (PMID 33511112, 2020).
mood disorder (1 paper, 2020). A cognitive disorder a disturbance in which the person's mood is hypothesized to be the main underlying feature. "A survey of Chinese Han people has shown an association between specific ALKBH5 polymorphisms and MDD, raising the possibility that ALKBH5 is involved in conferring a higher risk of this mood disorder." (PMID 32984403, 2020).
myeloid leukemia (1 paper, 2023). A clonal proliferation of myeloid cells and their precursors in the bone marrow, peripheral blood, and spleen. "Previous studies have shown a critical role for ALKBH5 in myeloid leukemia." (PMID 37742191, 2023).
myopia (1 paper, 2025). "Does high myopia lead to the downregulation of ALKBH5 and FTO expression by activating other signaling pathways?" (PMID 41315216, 2025). "However, why is ALKBH5 and FTO expression downregulated in nuclear cataract patients with high myopia?" (PMID 41315216, 2025). "Additionally, the expression of m6A-related enzymes, particularly the demethylases ALKBH5 and FTO, was downregulated, while methyltransferase METTL14 was upregulated in patients with high myopia." (PMID 41315216, 2025).
nasopharyngeal carcinoma (1 paper, 2024). A carcinoma arising from the nasopharyngeal epithelium. "This study is the first to explore the malignant biological effects of the combined action of demethylase FTO and ALKBH5 in nasopharyngeal carcinoma." (PMID 38263362, 2024).
neutropenia (1 paper, 2024). A decrease in the number of neutrophils found in the blood. "Our findings revealed the new role of ALKBH5 and m6A RNA demethylation in neutrophil immunobiology and the antibacterial innate defense, providing insight into and potential intervention strategies for neutropenia or neutrophil-associated disorders." (PMID 38114747, 2024). "Our findings indicate potential applications of the ALKBH5–m6A RNA demethylation–G-CSFR axis in rescuing neutropenia or low G-CSFR expression." (PMID 38114747, 2024).
oncocytomas (1 paper, 2021). "FTO and ALKBH5 transcript levels were significantly higher in ccRCC compared to oncocytoma (p = 0.0088 and p < 0.0001, respectively)." (PMID 34683137, 2021). "In IPO Porto’s cohort, FTO and ALKBH5 transcript levels discriminated ccRCC from oncocytomas." (PMID 34683137, 2021). "FTO and ALKBH5 immunostaining significantly differed between RCC subtypes and oncocytomas (including detailed statistical analysis)." (PMID 34683137, 2021). "In summary, we showed that FTO and ALKBH5 are differentially expressed among different RCC subtypes and oncocytomas, eventually proving useful for discrimination between malignant and benign renal cell tumors, as well as for prognostic assessment." (PMID 34683137, 2021). "ALKBH5 and FTO transcript and protein expression were evaluated in a series of primary RCC (n = 120) and 40 oncocytomas selected at IPO Porto." (PMID 34683137, 2021). "Considering the role of m6A modification and its erasers in carcinogenesis, we hypothesized that demethylating enzymes, FTO and ALKBH5, might be potential biomarkers with distinct roles in different RCC subtypes and oncocytomas." (PMID 34683137, 2021). "Furthermore, FTO and ALKBH5 immunoexpression differed among RCC subtypes, with higher expression levels found in ccRCC comparatively to the other RCC subtypes and oncocytomas." (PMID 34683137, 2021). "Interestingly, ccRCC displayed higher FTO and ALKBH5 mRNA levels compared to other RCC subtypes, which were able to discriminate ccRCC from oncocytomas." (PMID 34683137, 2021). "Thus, FTO and ALKBH5 expression alterations found among different RCC subtypes and oncocytomas do not seem to derive from copy number variations." (PMID 34683137, 2021).
oral epithelial dysplasia (1 paper, 2023). "Moreover, the role of FTO and ALKBH5 in oral precancerous lesions, especially in oral epithelial dysplasia (OED), has never been studied." (PMID 36582218, 2023).
osteoarthritis (1 paper, 2023). A noninflammatory degenerative joint disease occurring chiefly in older persons, characterized by degeneration of the articular cartilage, hypertrophy of bone at the margins and changes in the synovial membrane. "Knocking out the Alkbh5 gene in mouse MSCs aggravated osteoarthritis, while boosting Alkbh5 expression in MSCs reduced osteoarthritis progression." (PMID 37524872, 2023).
osteonecrosis (1 paper, 2021). A none disease characterized by death of bone tissue due to a lack of blood supply. "Interestingly, the m6A methyltransferase METTL14 was obviously down-regulated in osteonecrosis tissues and BMSCs from SONFH patients, while the demethylase ALKBH5 was up-regulated in SONFH tissues, but not in SONFH BMSCs." (PMID 34910686, 2021).
ovarian tumor (1 paper, 2024). "Our experiments confirmed that the transcription factor CREB, as a classic downstream molecule of FSH, upregulates the level of ALKBH5 in ovarian tumors, ultimately leading to EMT occurrence." (PMID 38505602, 2024). "In human specimen, we also confirmed that FSHR, ALKBH5 and Snail protein expression showed significant upregulation in ovarian tumors, compared to normal ovarian tissue, m6A content in total mRNA was higher than those in ovarian tumors." (PMID 38505602, 2024). "Upregulation of FSHR, ALKBH5, Snail was observed in ovarian tumor." (PMID 38505602, 2024). "Our study revealed that FSH promoted metastasis in ovarian tumors through the EMT process, with ALKBH5-induced demethylation of m6A modifications in Snail mRNA playing a critical role in this procedure." (PMID 38505602, 2024).
pancreatic neuroendocrine neoplasm (1 paper, 2023). A neoplasm with neuroendocrine differentiation that arises from the pancreas. "However, the specific role of ALKBH5 in pancreatic neuroendocrine neoplasms (pNENs) remains largely unknown." (PMID 37858219, 2023).
pancreatic neuroendocrine tumor (1 paper, 2024). Pancreatic endocrine tumor, also known as pancreatic neuroendocrine tumor (PNET), describes a group of endocrine tumors originating in the pancreas that are usually indolent and benign, but may have the potential to be malignant. "ALKBH5 also exhibits upregulated expression in pancreatic neuroendocrine tumors (pNENs), playing a critical role in tumor growth and lipid metabolism." (PMID 39192357, 2024).
plasmacytoma (1 paper, 2020). Plasmacytoma is a localized mass of neoplastic monoclonal plasma cells that represents approximately 5% of all plasma cell neoplasms. "Mechanistically, ALKBH5 removes the m6A marks, increases the stability of mRNA, and enhances the expression of plasmacytoma variant translocation one through inhibiting its YTHDF2 binding, resulting in increased OS cell proliferation rates both in vitro and in vivo." (PMID 33511112, 2020).
Premature ovarian insufficiency (1 paper, 2022). Amenorrhea due to loss of ovarian function before the age of 40. "Among readers of m6A methylation, studies confirmed that the protein level of FTO, but not ALKBH5, was significantly decreased in human aged ovaries and in ovaries of women diagnosed with premature ovarian insufficiency." (PMID 35346019, 2022).